INS (insulin)
Diseases named in the same sentence as INS in open-access papers (continued):
Sharing a sentence is not in itself a finding about the gene and the disease.
Hypoglycemia (continued). "In HH due to the inhibitory effect of insulin on lipolysis and ketogenesis there is suppressed ketone body formation in the presence of hypoglycaemia thus leading to increased risk of hypoglycaemic brain injury." (PMID 29280746, 2017). "Altered pharmacokinetics of anti-diabetic agents in CKD patients, decreased renal clearance, peripheral degradation of insulin, and impaired renal gluconeogenesis are all predisposed to the occurrence of hypoglycemia." (PMID 29100450, 2017). "The fear of hypoglycemia has been associated with various self-management strategies including reduction in insulin use and increased energy intake." (PMID 28611672, 2017). "This aims to decrease insulin infusion requirements, provide background insulin once intravenous insulin is discontinued, and reduce the risk of hypoglycaemia postcessation of insulin infusion." (PMID 28659865, 2017). "Patients receiving high doses of insulin prior to rewarming were at the greatest risk of hypoglycemia during the rewarming phase." (PMID 29075530, 2017). "Outside of pregnancy, long-acting insulin analogues improve glycaemic control, and are associated with lower rates of hypoglycaemia than human insulins." (PMID 28100192, 2017). "These drugs stimulate insulin secretion but have the advantage that they carry a low risk of causing hypoglycaemia, which is a common side effect of insulin treatment." (PMID 28551699, 2017). "Our intravenous regimen combining an infusion of insulin plus glucose effectively reduced serum potassium levels compared to previous studies and associated a low risk of symptomatic hypoglycemia and other complications." (PMID 28245289, 2017). "An alternative was sought owing to high insulin costs, inconvenience, and the probability of a higher risk of hypoglycemia." (PMID 28771572, 2017). "Regarding the use of insulin, 21.9% of the older adults used a variable dose of this medication, which can increase the risk of hypoglycemia." (PMID 28658367, 2017). "Congenital Hyperinsulinism (CHI) is a significant disorder of hypoglycaemia caused by excessive and unregulated insulin secretion." (PMID 28532504, 2017). "Acute severe insulin-induced hypoglycaemia (<2.3 mM, ≤5 days) causes an adaptive increase in mRNA and protein levels of neuronal and blood-brain barrier (BBB) glucose transporters most likely to ensure adequate glucose supply to neurons." (PMID 28421113, 2017). "The intranasal route of insulin administration thus bypasses uptake into the bloodstream and so circumvents the risk of systemic hypoglycemia that is associated with peripheral administration." (PMID 28291957, 2017). "Another study suggested that glyburide is as effective as insulin, but the risk of macrosomia, neonatal hypoglycemia, and fetal birth weight were higher." (PMID 28930827, 2017). "Given the reduced risk for hypoglycemia with the glucagon-like peptide-1 receptor agonists relative to insulin and sulfonylureas, the former was added in some cases in order to withdraw the latter two." (PMID 30291062, 2017). "Concurrent reduction of prandial insulin dosing is required to reduce the risk of severe hypoglycemia." (PMID 28167928, 2017). "Hypoglycemia was a major concern for those on insulin where shivering, dizziness, loss of consciousness and falls were reported." (PMID 28405339, 2017). "The activating p.Glu17Lys mutation in AKT2, a kinase mediating many of insulin’s metabolic actions, causes hypoinsulinemic hypoglycemia and left-sided hemihypertrophy." (PMID 28541532, 2017). "It was suspected that she was receiving an adequate amount of basal and premeal insulin but that the most likely cause of late evening and early morning hypoglycemia was an insufficient plasma cortisol concentration between midnight and 6 am." (PMID 28748191, 2017). "With the whole evaluation, we confirmed that in a Chinese population, biochemical postprandial hypoglycemia was associated with higher levels of both insulin sensitivity and insulin secretion." (PMID 28913363, 2017).
Hypoglycemia (continued). "In the multivariate time-dependent Cox regression analysis, meglitinide, as well as sulfonylurea and insulin, increased the risk of hypoglycemia after risk adjustments (all p < 0.001)." (PMID 29100450, 2017). "Newer, longer acting, basal insulin analogs have superior pharmacodynamic profiles, delayed onset and longer duration of action but low risk of hypoglycemia, albeit at higher costs." (PMID 28167928, 2017). "Multiple causes of hypoglycemia including exogenous insulin use, an insulinoma, low glycogen stores, adrenal insufficiency, renal insufficiency, insulin autoimmune syndrome, and hypothyroidism were considered by the Endocrinology Service." (PMID 29721512, 2017). "Both insulin and metformin are considered safe for use in pregnancy, but can be associated with unwanted side effects such as gastrointestinal disturbances and hypoglycemia." (PMID 28475161, 2017). "Glucagon, in high doses (over 1 mg), can cause rebound hypoglycemia due to a paradoxical increase in insulin secretion." (PMID 29280746, 2017). "Third, we did not demonstrate the underline mechanisms of older male patients who had a higher risk of nocturnal hypoglycemia when started on insulin intensive therapy." (PMID 28271075, 2017). "While DPP-4 inhibitor and time-varying ESRD predicted a lower risk of death, factors such as age, male gender, insulin use, hypoglycemia and other baseline comorbidities all predicted mortality." (PMID 29100450, 2017). "Causes of hypoglycemia were various, mainly including insulin or oral antidiabetic drugs abuse (65%) and neuroendocrine carcinoma (16%)." (PMID 28534234, 2017). "The risk of hypoglycaemia associated with the increase in exercise-induced insulin sensitivity is mitigated through reduction of endogenous insulin production, which additionally mediates increased glycogenolysis and fatty acid oxidation." (PMID 27287376, 2016). "Although anti-diabetic drugs, such as thiazolidinediones (TZD) improve insulin sensitivity, they are unfortunately associated with a risk of weight gain and hypoglycemia." (PMID 27070585, 2016). "Such a strict glycemic control is often challenging to reach since insulin is associated with an increased risk for hypoglycemia and weight gain." (PMID 27421257, 2016). "✔During therapy with insulin in combination with oral antidiabetic medications that can cause hypoglycemia, the patient must be educated about early detection of hypoglycemic symptoms and in the corrective actions to be taken if it occurs." (PMID 27546934, 2016). "Short-acting insulin analogs can be administered only after meal consumption to reduce risk of hypoglycemia if a meal is missed in patients with irregular eating pattern." (PMID 28031949, 2016). "The risk of hypoglycaemia is very low for liraglutide as its effects on insulin secretion are glucose dependent." (PMID 27252647, 2016). "SQ Lispro insulin caused hypoglycemia only at higher doses if the nutritional source was discontinued." (PMID 26819233, 2016). "This compromised physiological and behavioural response to falling blood glucose concentrations is arguably the more fatal arm of impaired glycaemic control in T2DM, with hypoglycaemia being a major cause of mortality in insulin-treated patients." (PMID 27044683, 2016). "Short-acting insulin secretagogues, such as repaglinide and nateglinide, have been shown to be effective with a low risk of hypoglycemia during the fasting period, particularly given their short duration of action." (PMID 27148163, 2016). "Congenital hyperinsulinism (CHI) is a disorder caused by dysregulated insulin secretion from the beta cells of the pancreas and is the major cause of hypoglycaemia during infancy and childhood." (PMID 27087264, 2016). "Type 1 diabetes patients with defective glucagon and adrenaline response to hypoglycaemia have a 25-fold or greater increased risk of iatrogenic hypoglycaemia during intensive insulin therapy." (PMID 27843452, 2016).
Hypoglycemia (continued). "In the short-term the greatest risk is due to hypoglycemia, which occurs largely due to over-delivery of insulin or to exercise." (PMID 30740333, 2016). "Impaired counter-regulatory responses and inappropriately high insulin levels increase the risk of hypoglycaemia during or after exercise." (PMID 27287376, 2016). "A recent study demonstrated that the 1,5-AG level is negatively associated with hypoglycemia in patients with well-controlled DM receiving insulin therapy." (PMID 27729086, 2016). "The physiological increase in insulin secretion and insulin sensitivity that occurs in early gestation increases the risk of hypoglycemia in women who conceive following bariatric surgery." (PMID 27488114, 2016). "Insulin therapy has several disadvantages including multiple daily injections, the risk of hypoglycemia, and maternal weight gain." (PMID 27597988, 2016). "The risk of inducing hypoglycemia is low with SGLT-2 inhibitors because of their insulin-independent action and hence forms an attractive class for managing patients with type 2 DM during Ramadan." (PMID 27642611, 2016). "Since chronic insulin production leads to increases in weight and an increased risk of hypoglycemia, SUs have been discouraged as early-use agents." (PMID 27417914, 2016). "Some fluoroquinolones cause hypoglycemia by blocking ATP-sensitive potassium channels (KATP) in pancreatic β-cells leading to stimulation of insulin secretion." (PMID 26649323, 2016). "Our network meta-analysis suggested that all GLP-1 RAs significantly increase the risk of hypoglycemia compared with placebo (except for albiglutide), and reduce the risk of hypoglycemia compared with insulin (except for dulaglutide) and SU." (PMID 27158818, 2016). "Incretin mimetics include glucagon-like peptide 1 (GLP1) analogs and agonists (exenatide, lixisenatide and liraglutide), which increase insulin secretion and suppress glucagon secretion in a glucose-dependent manner, with reduced risk of hypoglycemia." (PMID 26872083, 2016). "An effective strategy for patients using multiple daily injections would be to administer long-acting insulin with a meal at sunset and to reduce the dose by 20% to reduce the risk of hypoglycemia." (PMID 27148163, 2016). "Overall, BGTS utilization was greatest in claimants receiving therapy associated with a pre-defined high risk of hypoglycemia (e.g., SU, basal + bolus insulin regimens)." (PMID 26972690, 2016). "Evidence suggests that insulin analogues show greater efficacy, cause fewer hypoglycemia episodes and promote a better quality of life than human insulin." (PMID 27907034, 2016). "During intense exercise, insulin has to be reduced and/or carbohydrates have to be supplemented to avoid hypoglycemia due to the activation of glucose-transporter type 4 (GLUT 4) caused by insulin injection and muscle contraction." (PMID 27517956, 2016). "Duration of insulin therapy was associated with overall, nocturnal and severe hypoglycaemia in patients with T2D." (PMID 27161418, 2016). "In contrast, an antidiabetic drug that uses incretin as a mediator is expected to reduce the risk of hypoglycemia because stimulation of insulin secretion by incretin depends on the blood glucose level." (PMID 27491540, 2016). "Nevertheless, hypoglycemia episodes are associated with glucocorticosteroid deficiency resulting in enhanced insulin sensitivity of target tissues, increased glycolysis, and reduced glycogenesis and gluconeogenesis." (PMID 27525273, 2016). "In our analysis, the inclusion of information on hypoglycemia and treatment with ≥ 2 insulin injections/day as risk markers of hypoglycemia risk in the ADA/EASD strategy results in similar percentages of patients corresponding to each HbA1c target." (PMID 26887662, 2016). "Further, NPH insulin is associated with an increased risk of hypoglycemia relative to other basal insulin regimens, independent of its greater dosing frequency." (PMID 26972690, 2016).
Hypoglycemia (continued). "Of these about 10 % are especially sensitive to insulin and have defective counter-regulatory hormonal responses, putting them at higher risk of neuroglycopenia due to severe hypoglycemia." (PMID 27061400, 2016). "There are several different causes of hypoglycemia, including inappropriate diet, irregular physical activity and unsuitable insulin treatment of diabetes." (PMID 26918849, 2016). "The majority of patients (170; 85%) were on sulphonylureas or on insulin and therefore at risk of developing hypoglycaemia." (PMID 27380786, 2016). "The adjustment of insulin dose is instructed to achieve an optimal balance between glycemic control and the risk of hypoglycemia as dictated by clinical practice." (PMID 27009108, 2016). "SPRINT was deliberately designed to target nutrition to 60–70 % or lower for control, which reduced insulin requirements and thus risk of hypoglycemia." (PMID 27025951, 2016). "Insulin degludec showed similar rates of glycemic control but, again, with reduced risk of confirmed nocturnal hypoglycemia as well as of severe adverse events." (PMID 26740822, 2016). "Our meta-analysis confirms that compared to other hypoglycaemic drugs, there is a serious risk of hypoglycaemia with insulin." (PMID 27391319, 2016). "Just under half reported having experienced hypoglycaemia, and there was a strong association between hypoglycaemia and insulin use." (PMID 27380790, 2016). "In general, addition of insulin to the treatment regimen, longer duration of insulin use, and intensive treatment increase the risk of hypoglycemia." (PMID 28702246, 2016). "The low rate of incretin therapies use is also noteworthy, despite data showing that they are associated with a better HbA1c control and a lower risk of hypoglycemia and weight gain compared to insulin treated patients." (PMID 27453733, 2016). "On the other hand, in patients inject insulin the occurrence of hypoglycemia increases the fall-related fractures, there is a direct association between daily insulin need and low BMD." (PMID 27891497, 2016). "In Type 1 diabetics undergoing controlled experimental hypoglycemia caused by insulin infusion, MCT improve several cognitive outcomes." (PMID 27458340, 2016). "Prolonged usage of insulin often leads to insulin insensitivity and insulin resistance of the cell as well as other daunting side effects such as the risk of hypoglycemia." (PMID 27034931, 2016). "In contrast, patients on IDegAsp had a significantly lower risk of nocturnal-confirmed hypoglycemia compared with those on IGlar; likely the result of the flat, stable and ultra-long action profile of the basal insulin component of IDegAsp." (PMID 27760129, 2016). "Compared with insulin, exe_lar (OR 0.36, 95%CI: 0.21, 0.62) and exenatide (OR 0.63, 95%CI: 0.51, 0.79) were associated with less hypoglycemia." (PMID 27158818, 2016). "Within 90 min to 3 h, the late symptoms (sweating, tremor, trouble concentrating, loss of consciousness and hunger) appears due to high insulin secretion causing hypoglycemia." (PMID 27683791, 2016). "In trials comparing IDegAsp BID with BIAsp 30 highlighted the improved FPG-lowering ability of IDegAsp at comparable total insulin doses and significantly lower risk of overall confirmed and nocturnal hypoglycemia." (PMID 27760129, 2016). "Patients receiving insulin concomitant with moxifloxacin have a significantly higher risk of hypoglycemia in Taiwan." (PMID 26649323, 2016). "It has been recognized that the risk of hypoglycemia is one of the most significant factors that limit optimization of insulin therapy." (PMID 28702246, 2016). "Insulin and sulfonylureas confer a fourfold higher risk of being hospitalized for hypoglycemia in diabetic adults, leading to an underestimation of the hidden costs associated with prescribing these agents." (PMID 27648831, 2016). "Due to the increased risk of hypoglycemia in these patients, insulin has been considered the safest antidiabetic agent." (PMID 27471550, 2016).
Hypoglycemia (continued). "Insulin autoimmune syndrome is also known as Hirata disease, which is a rare cause of hypoglycemia characterized by high levels of endogenous insulin autoantibodies." (PMID 27065949, 2016). "It is highly related to the risk of hypoglycemia while titrating insulin dose in these patients with advanced insulin therapy." (PMID 25621692, 2015). "GLP-1 receptor agonists can increase insulin release and inhibit glucagon secretion with a low risk of hypoglycemia." (PMID 26157708, 2015). "If patient sets the duration of insulin action time less than the actual time, it will increase the risk of hypoglycemia." (PMID 26550021, 2015). "For example, advanced age, low BMI, poor glycaemic control, cognitive impairment, current use of sulphonylureas and current insulin use, and renal failure were reported to be associated with hypoglycaemia." (PMID 26504840, 2015). "Compared to Neutral Protamine Hagedorn (NPH) and Regular insulin, insulin Lispro can decrease the risk of hypoglycemia." (PMID 26157708, 2015). "Similar to previous studies, insulin was associated with an exceptionally high incidence of hypoglycemia, and the incidence was high in patients using SU agents or glinides as OHA monotherapy." (PMID 26566411, 2015). "In a cross-sectional study of 126 adults evaluated on average 5.8 years after TBI, 57% were found to have GHD or GHI (GH insufficiency, defined as response to insulin-induced hypoglycemia between 3–10 ng/mL) associated with IGF-I SDS < −2.0." (PMID 26287247, 2015). "Insulin treatment, although widely used, is labor-intensive in nature and carries a significant risk of hypoglycemia." (PMID 28702223, 2015). "It is hoped that our data will serve as a reference that helps in formulating insulin therapy which is less associated with hypoglycemia in type 1 diabetic patients." (PMID 26625003, 2015). "Hypoglycemia is a common side-effect of insulin therapy and is associated with significant mortality and morbidity rates in the diabetic population." (PMID 25945273, 2015). "All these limitations, combined with the inherent ability of insulin therapy to cause hypoglycemia and weight gain, stimulated the development of the new insulin analogues, glargine and detemir." (PMID 26136850, 2015). "For all patients with unexpected hypoglycemia, insulin overdose was the initially suspected cause of hypoglycemia." (PMID 25961056, 2015). "Excessive insulin secreting cells in insulinomas over-release insulin into the blood and resultant hyperinsulinaemia causes hypoglycaemia leading to a series of severe clinical signs and symptoms including permanent neurological damage and even death." (PMID 26182357, 2015). "When blood glucose concentrations are elevated, current guidelines recommend administering exogenous insulin, which is associated with substantial risks of hypoglycaemia and perturbations in blood glucose." (PMID 25613747, 2015). "Hypoglycaemia is more common in patients with RI because of decreased renal gluconeogenesis, and in particular, overexposure to insulin secretagogues or exogenous insulin is often associated with an increased risk of hypoglycaemia." (PMID 26067186, 2015). "Similar trends were found in analysis with combined therapies, a strong association with not only insulin but also SU agents and glinides, a low risk of hypoglycemia when using DPP-4 inhibitors." (PMID 26566411, 2015). "Recognizing these changes and applying principles of good prescribing is needed to reduce risk of hypoglycemia in patients on insulin or insulin secretagogues." (PMID 26239457, 2015). "Metformin treatment when compared with insulin treatment showed less maternal hypertensive complications and less risk of neonatal hypoglycemia with few neonatal intensive care admissions." (PMID 25874236, 2015). "Other glucose-lowering agents, particularly the insulin secretagogues, the sulfonylureas and glinides, can also cause hypoglycemia, although are seldom reviewed in relation to driving performance." (PMID 28702227, 2015).